VAMP1 (vesicle associated membrane protein 1)
Description:
Involved in the targeting and/or fusion of transport vesicles to their target membrane.
Synonyms: VAMP-1; SYB1; CMS25; SAX1; SPAX1
Tractability: Antibody: its Gene Ontology location is reachable by antibodies, with high confidence; UniProt predicts a signal peptide or a membrane-spanning region. PROTAC: ubiquitination databases record sites on it.
Gene: Protein-coding gene on chromosome 12 (6,462,237 to 6,470,677, reverse strand). Ensembl gene ENSG00000139190.
Subcellular location: Cytoplasmic vesicle, secretory vesicle, synaptic vesicle membrane (Isoform 1); Synapse, synaptosome; Cytoplasmic vesicle membrane (Isoform 2); Mitochondrion outer membrane (Isoform 3)
Pathways (Reactome):
Disease: Toxicity of botulinum toxin type D (botD); Toxicity of botulinum toxin type F (botF); Toxicity of botulinum toxin type G (botG)
Gene Ontology:
Molecular function: protein binding; SNAP receptor activity; syntaxin binding
Biological process: neurotransmitter secretion; SNARE complex assembly; vesicle fusion; vesicle-mediated transport
Cellular component: azurophil granule membrane; cytosol; specific granule membrane; tertiary granule membrane; plasma membrane; presynaptic membrane; SNARE complex; synaptic vesicle membrane; cytoplasmic vesicle membrane; membrane; mitochondrial outer membrane; synapse; transport vesicle
Genetic constraint (gnomAD): Loss-of-function variants: 13 observed, 16.12 expected, observed/expected ratio (o/e) 0.81, 90% interval 0.52 to 1.28. The upper end of that interval is the gene's LOEUF score, 1.28, which puts it in group 5 of 6, group 1 being the genes least tolerant of losing a copy. Missense variants: 105 observed, 140.27 expected, observed/expected ratio (o/e) 0.75, 90% interval 0.64 to 0.88. Synonymous variants: 34 observed, 49.21 expected, observed/expected ratio (o/e) 0.69, 90% interval 0.52 to 0.92.
Homologues: Orthologues: chimpanzee VAMP1 (100% identical), macaque VAMP1 (99% identical), guinea pig VAMP1 (98% identical), rabbit VAMP1 (98% identical), mouse Vamp1 (95% identical), rat Vamp1 (92% identical), dog VAMP1 (87% identical), Drosophila melanogaster Syb (54% identical), Caenorhabditis elegans snb-2 (43% identical), Caenorhabditis elegans snb-5 (19% identical), Caenorhabditis elegans snb-6 (19% identical), Caenorhabditis elegans snb-7 (19% identical). Paralogues in human: VAMP2 (80% identical), VAMP3 (57% identical), VAMP7 (31% identical), VAMP8 (28% identical), VAMP4 (27% identical), VAMP5 (27% identical), YKT6 (24% identical), SEC22B (23% identical), SEC22A (17% identical), SEC22C (17% identical).
Diseases named in the same sentence as VAMP1 in open-access papers:
VAMP1 is named in the same sentence as 30 diseases in open-access papers, as found by Europe PMC text mining. Sharing a sentence is not in itself a finding about the gene and the disease. The quoted sentences say what the papers report.
schizophrenia (6 papers, 2012 to 2023). A major psychotic disorder characterized by abnormalities in the perception or expression of reality. "Two core SNARE proteins, the synaptosomal-associated protein of 25 kDa (SNAP25) and the vesicle-associated membrane protein (VAMP1, also known as synaptobrevin), were both significantly down-regulated in schizophrenia." (PMID 22558445, 2012). "In conclusion, our study demonstrates that schizophrenia is associated with lower levels of cytoplasmic Rbfox1 isoform in prefrontal PVIs which could account for lower Vamp1 mRNA levels in the same neurons." (PMID 37398467, 2023). "Here, we tested the hypothesis that schizophrenia is associated with lower levels of cytoplasmic isoform of Rbfox1 protein and its target transcript Vamp1 in prefrontal PVIs." (PMID 37398467, 2023). "In concert, these findings support the regulatory role of cytoplasmic Rbfox1 on Vamp1 levels in human PFC and suggest that lower cytoplasmic Rbfox1 protein levels contribute to lower Vamp1 mRNA levels in PVIs in schizophrenia." (PMID 37398467, 2023). "Consistent with this idea, our study shows a positive correlation between the protein levels of cytoplasmic Rbfox1 and the mRNA levels of Vamp1 in PVIs, which are both lower in schizophrenia." (PMID 37398467, 2023). "There were 8 DEGs (Ldoc1, Nefh, Parm1, Ptpro, Pvalb, Spp1, Synpr, Vamp1) shared by the schizophrenia and epilepsy gene sets, suggesting a common molecular basis between the two disorders." (PMID 37545878, 2023). "In a subset of this cohort, Vamp1 mRNA levels in PVIs were also significantly lower in schizophrenia and were predicted by lower cytoplasmic Rbfox1 protein levels across individual PVIs." (PMID 37398467, 2023). "On the other hand the levels of VAMP-1 were affected to a significant degree, emphasising the potential parallels between the effects of poly(I:C) and the changes reported in schizophrenia." (PMID 22681877, 2012). "Finally, the levels of Vamp1 mRNA, a major target transcript of cytoplasmic Rbfox1, were lower in PVIs in schizophrenia and were predicted by lower cytoplasmic Rbfox1 protein levels across these neurons." (PMID 37398467, 2023). "To investigate if lower cytoplasmic Rbfox1 protein levels predict lower Vamp1 mRNA levels in PVIs in schizophrenia, we first explored whether Vamp1 is highly expressed in these neurons in human PFC." (PMID 37398467, 2023). "Together, these findings demonstrate that Vamp1 mRNA levels are lower in PVIs in schizophrenia and suggest that this alteration could be due to deficits in cytoplasmic Rbfox1 levels in these neurons." (PMID 37398467, 2023). "Together, these findings support the hypothesis that the nature of Rbfox1 pathway alterations in schizophrenia includes lower levels of cytoplasmic Rbfox1 protein isoform and of its target Vamp1 mRNA in prefrontal PVIs." (PMID 37398467, 2023). "Finally, we investigated the relationship between the levels of cytoplasmic Rbfox1 protein and Vamp1 mRNA in PVIs in schizophrenia." (PMID 37398467, 2023). "To test this hypothesis, we applied a novel technical strategy that combines multi-label in situ hybridization and immunohistochemistry in postmortem human brain to quantify the levels of cytoplasmic Rbfox1 isoform and Vamp1 mRNA in the same PVIs in the PFC of individuals with schizophrenia." (PMID 37398467, 2023). "Therefore, examining the levels of cytoplasmic Rbfox1 isoform and Vamp1 mRNA in PVIs could provide important insights into molecular mechanisms underlying impaired cortical inhibition and deficient PFC gamma oscillations in schizophrenia." (PMID 37398467, 2023). "The mean density of Vamp1 mRNA grains was significantly (F1,9=5.9, P = 0.038) 20% lower in PVIs in PFC of schizophrenia relative to comparison subjects." (PMID 37398467, 2023).
Ataxia (3 papers, 2015 to 2022). Ataxia refers to impaired coordination of voluntary muscle movement. "This suggests that the dominant spinocerebellar ataxia previously reported in a family with a heterozygous VAMP1 mutation may not be caused by haploinsufficiency as originally suggested but a different mechanism, e.g., dominant negative." (PMID 28600779, 2017).
congenital myasthenic syndrome (3 papers, 2017 to 2023). Congenital myasthenic syndrome (CMS) is a group of genetic disorders of impaired neuromuscular transmission at the motor endplate characterized by fatigable muscle weakness. "In humans, Vamp1 mutations have been identified in people with hereditary spastic ataxia 1 and congenital myasthenic syndrome." (PMID 37309812, 2023).
Alzheimer disease (2 papers, 2015 to 2022). A progressive, neurodegenerative disease characterized by loss of function and death of nerve cells in several areas of the brain leading to loss of cognitive function such as memory and language. "We performed a case-control association study of the 5 VAMP1 expression regulating polymorphisms in 4,667 Alzheimer’s disease patients and 6,175 controls to determine their contribution to Alzheimer’s disease risk." (PMID 25881291, 2015). "We found that polymorphisms associated with increased brain VAMP1 transcript levels conferred higher risk for Alzheimer’s disease than those associated with lower VAMP1 transcript levels (p = 0.03)." (PMID 25881291, 2015). "This study has primarily focused on the specific role of VAMP1 in Aβ secretion and its association with Alzheimer’s disease pathophysiology and susceptibility." (PMID 25881291, 2015). "Since deposition and oligomerization Aβ is a key pathological hallmark of the Alzheimer’s brain, our data led us to propose that genetic variation at the VAMP1 locus may be associated with altered susceptibility against Alzheimer’s disease." (PMID 25881291, 2015). "Overall, these data suggest that VAMP1 transcription across tissues may be controlled by polymorphisms located at several locations within VAMP1 and that, in the case of rs2072376, this regulation may be disrupted in the Alzheimer’s disease subgroup." (PMID 25881291, 2015). "Overall, these data are, at best, suggestive of a common polymorphism, rs2072376 (MAF = 41%), in VAMP1 that is associated with decreased cerebellar VAMP1 expression that may have a modest protective effect against Alzheimer’s disease." (PMID 25881291, 2015). "Moreover, we also report a modest protective association for a common VAMP1 polymorphism with Alzheimer’s disease risk (OR = 0.88, p = 0.03)." (PMID 25881291, 2015). "Here we have identified a strong association of common VAMP1 polymorphisms with VAMP1 cerebellar transcript levels in Alzheimer’s disease and control brains, with the strongest correlation at the 3′ end of the gene with increased VAMP1 expression (rs7390 and rs12964, all p < 2.4×10-7)." (PMID 25881291, 2015). "Genetically regulated VAMP1 expression in the brain may modify both Alzheimer’s disease risk and may contribute to Alzheimer’s pathophysiology." (PMID 25881291, 2015). "Sequencing the 28,440 base pair region containing VAMP1 (+/-20 kb) in 300 Alzheimer’s disease cases and 300 controls (95% power to detect all variants with MAF > 1%), we identified 10 variants, 5 of which were subsequently genotyped in the remaining case-control series (10,842 samples)." (PMID 25881291, 2015). "Moreover, we report a modest association of a common polymorphism, rs2072376 (MAF = 0.40), located at the 5′ end of VAMP1, with decreased risk for Alzheimer’s disease (OR = 0.88, p = 0.03)." (PMID 25881291, 2015). "This same polymorphism was associated with decreased cerebellar VAMP1 transcript levels (-β = -0.21; p = 0.02) and demonstrated functional repressor activity in vitro (p < 0.01), thus supporting our hypothesis that decreased VAMP1 expression may be protective against Alzheimer’s disease." (PMID 25881291, 2015).
epilepsy (2 papers, 2015 to 2023). A brain disorder characterized by episodes of abnormally increased neuronal discharge resulting in transient episodes of sensory or motor neurological dysfunction, or psychic dysfunction. "VAMP1 strongly co-localized with GAD65 positive boutons, particularly in the mainly soma-targeting boutons of stratum pyramidale, which play a key role in regulating pyramidal cell firing and hence in epilepsy." (PMID 24442865, 2015).
spastic ataxia (2 papers, 2018 to 2022). "In this study, there was no causative mutation associated with spastic ataxia, such as SACS/VAMP1/KIF1C/MARS2/MTPAP/AFG3L2(AR), detected." (PMID 35572931, 2022).
autism (1 paper, 2022). Persistent deficits in social interaction and communication and interaction as well as a markedly restricted repertoire of activity and interest as well as repetitive patterns of behavior. "We hypothesize that genes severely dysregulated in autism such as SCN1B, KCNAB3, FMN1, or VAMP1 might additionally contribute to the excitation-to-inhibition ratio affecting normal network function and circuitry." (PMID 35680911, 2022).
botulism (1 paper, 2017). A serious bacterial infection caused by botulinum toxin which is produced by Clostridium botulinum. "Previous work indicated that TeNT and BoNT have acted to select mutants of the VAMP-1 protein, which are resistant to their proteolytic activity and therefore to the neuroparalysis induced by tetanus and botulism." (PMID 29257047, 2017).
cervical dystonia (1 paper, 2013). "For example, botulinum toxin type B is a drug that targets VAMP-1 and has been approved for the treatment of cervical dystonia; however, the issue of toxicity and the ability to deliver to the site of virus replication remains a significant obstacle to be overcome." (PMID 24199805, 2013).
congenital myopathy (1 paper, 2017). "For example, we report two families with a severe congenital myopathy phenotype each with a different homozygous truncating mutation in VAMP1 inherited from healthy non-ataxic parents." (PMID 28600779, 2017).
episodic ataxia (1 paper, 2023). "Due to these nonepileptic events, molecular testing for episodic ataxia panel (CACNA1A, CACNB4, KCNA1, PNKD, PRRT2, SLAC1A3, VAMP1) was requested, and this came back normal." (PMID 37469362, 2023).
hypothyroidism (1 paper, 2024). Abnormally low levels of thyroid hormone. "In this study, utilizing MR analysis for the first time, we discovered that hypothyroidism can lead to changes in the expression levels of 26 plasma proteins, including CXCL13, VAMP1, and CXCL10, among which CXCL10 may mediate the impact of hypothyroidism on the risk of developing IPF." (PMID 39185418, 2024).
Kyphoscoliosis (1 paper, 2019). An abnormal curvature of the spine in both a coronal (lateral) and sagittal (back-to-front) plane. "Joint laxity and kyphoscoliosis were reported in association with VAMP1 and COL13A1 variants." (PMID 30808424, 2019).
Lambert-Eaton myasthenic syndrome (1 paper, 2023). Lambert-Eaton myasthenic syndrome (LEMS) is an autoimmune, presynaptic disorder of neuromuscular transmission characterized by fluctuating muscle weakness and autonomic dysfunction frequently associated with small-cell lung cancer (SCLC). "SYT2-CMS, SNAP25-CMS, VAMP1-CMS, UNC13A-CMS, RPH3A-CMS, and LAMA5-CMS are characterized by defects in the SNARE complex, and phenotypically similar to Lambert-Eaton myasthenic syndrome (LEMS)." (PMID 36835142, 2023).
migraine (1 paper, 2014). "It has been reported that both VAMP1 and VAMP2 are expressed in trigeminal ganglion neurons involved in migraine." (PMID 25010769, 2014).
scoliosis (1 paper, 2024). A congenital or acquired spinal deformity characterized by lateral curvature of the spine. "Finally, scoliosis itself is typically associated with mutations of the COLQ, VAMP1, and CHRNE (slow channel syndrome) genes rather than GFPT1 mutations." (PMID 39559672, 2024).
tetanus (1 paper, 2017). A serious infectious disorder that follows wound contamination by the Gram-positive bacterium Clostridium tetani. "Previously, rats and chickens were found to be resistant to tetanus because VAMP-1, which is the predominant form of VAMP in the spinal cord, is mutated at the TeNT cleavage site." (PMID 29257047, 2017). "It was found that rats and chicken are resistant to tetanus because VAMP-1 is the predominant isoform in the spinal cord and their VAMP-1 carry the peptide bond Val77-Phe78, not cleavable by TeNT, rather than the TeNT sensitive peptide bond Gln77-Phe78 present in most species, including humans." (PMID 29257047, 2017).
neurological diseases (4 papers, 2015 to 2022). "Among the relatively small number of top rated differentially regulated genes, there were at least 35 genes that have been shown to have neuron-specific functions or associated with various neurological diseases, including Vamp1, Vamp2 and Snap25 (synaptosomal-associated protein 25)." (PMID 30001398, 2018). "Therefore, while there is a precedent for abnormal VAMP1 expression with several unrelated neurological disorders, this is the study is the first to report a potentially protective effect of VAMP1." (PMID 25881291, 2015).
cancer (2 papers, 2019). A tumor composed of atypical neoplastic, often pleomorphic cells that invade other tissues. "Nonetheless, exosomal proteins previously reported to be associated with vesicle secretion in cancer cell line supernatants (RAP1A, RAP1B, VAMP1, MYH7, MYO18a, MYOLPF, MYO1E, VPS13B, HSP70) were identified in our samples." (PMID 30764491, 2019). "Additionally, we observed that the expression of cell death regulators such as CYLD, EZR, VAMP1, ANAX1, and FPR1 was increased in mild hyperthermia treated cancer cells, which was similar to LIUS treated cancer cells." (PMID 31355136, 2019).
tumor (1 paper, 2024). "Furthermore, eight target genes (COL4A3, FAM30A, FCRL5, MDM4, SYNE2, TNFRSF13C, TPTEP2, VAMP1) were systematically positively correlated with ESR2 expression patterns in tumor types with low ESR2 expression as a prognostic factor concerning OS or DFS." (PMID 39201394, 2024). "Notably, our findings highlight seven genes (FAM30A, MDM4, POU2AF1, SYNE2, TNFRSF13C, TPTEP2, VAMP1) presenting positive correlations with ESR2 expression patterns in all tumor types with high ESR2 expression as a positive prognostic factor with regard to OS or DFS." (PMID 39201394, 2024).
VAMP1 also shares sentences with these, for which no sentence is quoted: Astrocytoma (1 paper); autosomal dominant spastic ataxia (1); glioblastoma (1); hepatocellular carcinoma (1); hyperkyphosis (1); Hyperlordosis (1); infection (1); lymphoma (1); motor neuron disease (1); pheochromocytoma (1).